CDH1 (cadherin 1)
Diseases named in the same sentence as CDH1 in open-access papers (continued):
Sharing a sentence is not in itself a finding about the gene and the disease.
tumor (continued). "Among commonly reported differentially methylated genes in HPV-driven HNSCC are genes involved in cell-cycle regulation (CDKN2A, RASSF1, and CCNA1), cellular adhesion (CDH1, CDH8, CDH18, CDH15, CDH13, CDH19 and CDH23, ITGA4), and tumour progression (TIMP3)." (PMID 34835040, 2021). "The epithelial marker CDH1 was downregulated when SPHK1 was overexpressed, some tumour-related metabolic processes, such as cell invasion and migration, were promoted, and the EMT process was induced." (PMID 34857818, 2021). "On the contrary, our analysis revealed an opposite trend of alterations for CDH1 and CD22 within the explored neoplasms." (PMID 34202213, 2021). "Previous reports showed that EZH2 targets a cascade of tumour suppressors, such as CDX1, FOXC1, LATS2, CDH1 and DAB2IP." (PMID 33336896, 2021). "Expression of ITGA11 was negatively correlated with CDH1, whereas positively correlated with VIM or CDH2 in tumor samples of STAD from the TCGA and GSE66229 datasets." (PMID 34222028, 2021). "Nuclear miR-373 and miR-744 can bind the CDH1 (E-cadherin) and CCNB1 (cyclin B1) promoters, respectively, to induce expression and modulate tumor growth." (PMID 34199614, 2021). "Oncomine datasets demonstrated CDH1, CDH2, SNAI1, SNAI2, VIM, TWIST1 in 20 types of cancers between tumor and normal tissues." (PMID 31915310, 2020). "In qPCR array analyses, besides promoting the expression of CDH1, KH-3 treatment also induces the expression of CD82, a tumor metastasis suppressor." (PMID 32332873, 2020). "Recently, it has been reported that RASSF10 regulates epithelial cadherin (CDH1) expression, that is a tumor suppressive TGFβ-target and inhibits epithelial-to-mesenchymal transition (EMT)." (PMID 32047266, 2020). "In the next step, expression level of stemness relatedgenes (OCT4, SOX2, KLF4, c-MYC and NANOG) and EMTtranscription factors (CDH1, CDH2, SNAIL1, TWIST1,TWIST2 and ZEB1) were evaluated in all tumor samples andmammospheres." (PMID 31376329, 2020). "The correlations of ZNF750 with SNAI1, VIM, CDH2 and CDH1 were verified with our RNA sequencing data of 155 paired of ESCC and matched non-tumor tissues." (PMID 32042337, 2020). "DSTYK expression is positively proportional to the expression of TGF-β, mesenchymal markers vimentin (VIM) and N-cadherin (CDH2) in tumor tissues from human CRC patients, whereas it is inversely correlated to epithelial marker E-cadherin (CDH1) expression." (PMID 32982725, 2020). "If the CDH1 and PVRL2 are essential for tumor cells avoiding immune evasion, their expression should affect the survival of patients." (PMID 33304391, 2020). "MYC can induce miR-9-3 expression that targets E-cadherin (CDH1), a cellular adhesion protein essential for the cell-cell contact of the gastric epithelium, and promoting tumor cell migration and invasion, leading to EMT in GC." (PMID 32150871, 2020). "Several oncogenic kinase cascades impinge on Cdh1 function, further supporting a role for APC/CCdh1 in tumor suppression." (PMID 33306668, 2020). "In relation to the malignancy grade of the tumor, mRNA levels of SEMA3B, SEMA3C, SEMA3D, SEMA3G, PLXNA2, and CDH1 decreased while mRNA levels of SEMA3F, NRP1, ITGB3, ITGA5, and VEGFA increased with the increase of the tumor malignancy (p < 0.05)." (PMID 33036421, 2020). "IHC analysis of subcutaneous tumours generated by SPON2‐knockout SGC‐7901 cells revealed that compared with the controls, the levels of CDH1 expression increased, those of CDH2, VIM and p‐ERK1/2 decreased, and those of ERK1/2 were unchanged." (PMID 31691494, 2020). "We further compared the mRNA expression of CDH1, CDH2, SNAI1, SNAI2, VIM, TWIST1 between ccRCC tumor samples and adjacent normal tissues respectively based on RNA-sequence data from TCGA database." (PMID 31915310, 2020).
tumor (continued). "Considering PAH as a liver gene, we analyzed the expression levels of Cdh1 and PAH individually using The Cancer Genome Atlas (TCGA) data in liver hepatocellular carcinoma (LIHC) for which normal-tumor matched RNAseq expression data were available." (PMID 33260674, 2020). "SIRT2 has been shown to provide anti-tumor potential by deacetylating both CDC20 and CDH1 to promote their recruitment to the APC and cell cycle progression." (PMID 32805721, 2020). "We performed BioGRID analyses of the APC coactivators CDC20 and CDH1, which revealed that at least 69 proteins serve as APC substrates, with 60 of them identified as playing a role in tumor promotion and 9 involved in tumor suppression." (PMID 32805721, 2020). "CDH1 codes for E-cadherin and its downregulation contributes to tumor cell invasion by promoting EMT of the tumor cells." (PMID 33419253, 2020). "For example, known tumor suppressors or tumor-related genes (p16, RUNX3, MLH1, CDH1, etc.)are silenced by promoter methylation in GC and its precancerous lesions." (PMID 31959204, 2020). "CDH1 is a tumor suppressive regulator of cell adhesion in epithelial cells and prevents EMT that is an important step in tumor invasion." (PMID 32047266, 2020). "While E-cadherin (coded by CDH1) is considered a tumor repressor, mesenchymal marker N-cadherin (coded by CDH2) is regarded as a tumor facilitator in carcinomas." (PMID 33348918, 2020). "The expression level of miRNAs was also studied, since the miR200 family members (miR200a, miR200b, miR200c, miR141, miR429), miR34a, miR34b and miR203a are considered to play important roles in tumor cell migration by the regulation of ZEB1 and CDH1." (PMID 33419253, 2020). "We evaluated CDH1 expression by quantitative real-time PCR (RT-qPCR) in 33 IGC patients and found a significant downregulation in tumor tissues compared to normal counterparts (p-value = 0.025)." (PMID 31509966, 2019). "Herein, we focused on the epigenetic impact on OC formation by analysing the methylation levels of the RASSF1, PTEN, CDH1 and PAX1 tumour suppressor genes’ regulatory sequences." (PMID 31450846, 2019). "Using the gene expression data of NCI-60 human tumor cell lines as the training set, the ratio of VIM to CDH1 together with CLDN7 expression are identified as the best-fit pair of predictors to classify EMT phenotypes." (PMID 31121840, 2019). "Therefore, the CDH1 gene could be considered a very promising candidate for non-invasive LB-based diagnosis of malignant OC, but its potential for non-invasive investigation of benign tumour presence requires further analysis." (PMID 31450846, 2019). "UHRF1 is also associated with epigenetic silencing of various tumor suppressors and other tumor-related genes, including CDKN2A, RB, BRCA1, RASSF1, PPARG, APC, CDH1, and RGS2." (PMID 31064417, 2019). "To investigate this, we analyzed the correlations between well-known immune and tumor cell markers (CD45 or PTPRC, CD3, CD8, etc and CDH1, EPCAM) with ISGF3 subunits within the TCGA dataset." (PMID 30355451, 2018). "In conclusion, miR-219-5p promotes tumor growth and metastasis of HCC by regulating CDH1 and can serve as a prognostic marker for HCC patients." (PMID 29862272, 2018). "The differentially expressed genes in triphasic tumours relative to blastemal tumours included genes published as potential UB/CD markers: MUC1, PKHD1, KRT7, CDH1, and LIF." (PMID 29040332, 2017). "On the other hand, miR-4510 treatment led to an increase in several important regulators of β-catenin functions and tumor suppressors such as AXIN2, E-cadherin (CDH1), LRP1 and WNT5A." (PMID 28476031, 2017).
tumor (continued). "The current analyses comprising all eligible articles revealed that promoter methylation of the p16, CDH1, RUNX3, MLH1, RASSF1A, p15, APC, GSTP1, Reprimo, and MGMT was significantly higher in blood samples of patients with GC compared with non-tumor controls." (PMID 29100425, 2017). "CDH1 and EPHB3 are essential for an intact tissue architecture of the intestinal epithelium and possess tumor suppressor activity." (PMID 29155818, 2017). "A “Cadherin Switch” refers to the change from CDH1 to CDH2 and is considered to be the key factor in tumour invasion and metastasis." (PMID 29115924, 2017). "This provides the first evidence that CTCF inactivation in conjunction with inactivation of CDH1 and/or ZFHX3 and/or other candidate genes on 16q contributes to the development of poorer prognosis tumour subtypes." (PMID 28319062, 2017). "In contrast, the mRNA levels of tumor suppress genes (PTEN, BAK, and CDH1) were increased significantly after the blocking of ARPC2, which indicated that ARPC2 downregulated them." (PMID 28694563, 2017). "Classical epithelial markers, such as CDH1 and occludin (OCLN), were downregulated in the tumor bud samples compared to IEC and CCPT." (PMID 28687755, 2017). "Some researchers have found that Sip1 protein binds proximal E-boxes within the E-cadherin gene (cdh1) promoter, and CDH1 transcriptional down-regulation induces EMT in developmental processes and during tumor cell invasion and metastasis." (PMID 28470188, 2017). "In NR genome, promoters of the three tumor suppressors (RARB, CDH1, and EPCAM) were found to be almost exclusively unmethylated by methylation-specific PCR (MSP)." (PMID 28467809, 2017). "For example, the epithelial markers CDH1 and OCLN are down-regulated in tumor buds compared to the cancer cells in the center of the primary tumor, and up-regulated in the stroma of tumor budding compared to the stroma of regular cancer cells." (PMID 28687755, 2017). "At the molecular level, the epithelial biomarker CDH1 is downregulated, and the mesenchymal biomarkers N-cadherin (CDH2) and fibronectin (FN1) are upregulated in tumor buds, thus suggesting that tumor buds have mesenchymal characteristics." (PMID 28687755, 2017). "The expressions of CDH1 and CTNNB1 were significantly weaker in tumour tissue than normal bronchial epithelial cells." (PMID 29115924, 2017). "Importantly, aberrant activation of the PI3K/Akt signaling pathway has been observed in many types of human cancers, therefore a possible involvement of Cdh1 in negatively regulating this critical oncogenic pathway may underscore the emerging tumor suppressive role of Cdh1." (PMID 27462441, 2016). "Multivariate analysis shows that cytoplasmic CDH1 expression, nuclear HDAC3 expression, and tumor differentiation were independent prognostic factors for PC patients." (PMID 26918727, 2016). "To explore the mechanism behind the antitumor activity of grifolin, we performed a screening of genes related to tumor adhesion/invasion regulation, including MMP1,2,3,9,19, TIMP-1,2,3, CD44, CDH1 and PCDH10." (PMID 27626695, 2016). "E-cadherin, also known as cadherin 1 (CDH1), is a classical transmembrane cell-cell adhesion glycoprotein and a well-known tumor suppressor." (PMID 27129169, 2016). "M0 cells with normal cCGH profiles exhibited losses in genomic regions containing CDH1 (E-cadherin) and CTNNB1 (β-catenin), suggesting that they are indeed tumor cells." (PMID 26378808, 2015). "In tumor-adjacent normal breast tissues, the expressions of CTGF were also examined to positively correlate with FN1 and VIM and negatively correlate with CDH1." (PMID 26318291, 2015).
tumor (continued). "A few genes, such as Cdh1 and Neat1 possessed SEs in SCC-SC, T72D-ETS2-EpiSC and EpiSCs, reflective of their sustained high expression in normal and tumor tissue." (PMID 26590320, 2015). "However, the expression of these transcription factors were not directly associated with the differentiation status of tumor cells and consistent with this observation, significant association between the expression of CDH1 and transcription factors was not demonstrated." (PMID 26214683, 2015). "By RT-PCR of tumor samples, we documented that KB9520 treatment decreased the expression of the SLC16A3 and CD147 genes and increased the expression of the CDH1 gene." (PMID 26208479, 2015). "Table representing RNA expression change of CDH1 and KRT 20 after normal and tumor tissue derived DNA treatment." (PMID 26133168, 2015). "In this study, we used immunohistochemistry to study the expression of a panel of transcription factors (TWIST1, SNAI1/2, ZEB1 and ZEB2) and other genes intimately related to EMT (CDH1 and LAMC2) at the invasive tumor front of OSCC tissues." (PMID 26214683, 2015). "All of these genes are known to be involved in different aspects of breast carcinogenesis, which includes tumor suppression, HIC1, CDH1, CDH13, CDKN2, DNA repair, MGMT, apoptosis, PYCARD, TNFRSF10C, and cell cycle regulation, CCNA1." (PMID 25403427, 2014). "In our study, gene hypermethylation was detected most commonly in CDH1 and CDKN2A genes in central and peripheral parts of the tumor." (PMID 24782031, 2014). "For example, the methylation of some tumor related genes such as p16, DAPK, RAR-β, CDH1, and RASSF1A have been detected in circulating cell-free DNA." (PMID 25050929, 2014). "The coordinated upregulation or, not uncommonly, overexpression of ZEB1, ZEB2, SNAI1, and VIM and the downregulation of CDH1 indicated that EMT was under way, making the tumor cells assume a mesenchymal phenotype." (PMID 25157365, 2014). "Frequently methylated genes in HCC such as P16/CDKN2A, CDH1 and GSTP1 were also found to be similarly hypermethylated in our tumor samples." (PMID 25093504, 2014). "For LVI, the model identified seven CpGs from three genes as the most informative variables: CDH1 (sites 1, 2 and 4), CDH13 (sites 2 and 5) and methylated-in-tumour 3, MINT3 (sites 6 and 9)." (PMID 25052224, 2014). "A number of tumor suppressor genes acting in cell cycle, apoptosis, cell adhesion, and invasion are inactivated by hypermethylation such as CDH1 (cadherin 1) and MLH1 (mutL homolog 1)." (PMID 24729878, 2014). "Since all subjects carrying the ID 17 mutation are heterozygous for the CDH1 gene, our data indicated that the S190 individual, but not tumor cells of S10 and S46 patients, may exploit some compensatory mechanism that counteracts the E-cadherin down-regulation." (PMID 24204729, 2013). "Using human ILBC cell lines, primary tumors and pre-invasive lesions as a model, the present study aimed to determine the relevance of the newly proposed relationship between E-cadherin and BCL2 for tumor development driven by CDH1 inactivation." (PMID 24023670, 2013). "To circumvent this methodological limitation and to rule out the possibility that upregulation of BCL2 is restricted to the pre-invasive stage of tumor development driven by CDH1 inactivation, we evaluated E-cadherin and BCL2 immunoreactivity in LCIS lesions." (PMID 24023670, 2013). "Among them, seven genes, whose methylation was reported in different tumor models, appeared to be frequently methylated in primary cells of 38 MCL patients (SOX9, HOXA9, AHR, NR2F2, ROBO1, NPTX2 and CDH1)." (PMID 24252620, 2013). "Notable examples include E-Cadherin (CDH1), T-Cadherin (CDH13) and Proto-Cadherin 10 (PCDH10) which are recognized tumor-suppressor genes, and have been found to be hypermethylated in a number of human cancers." (PMID 23419152, 2013). "Thus, CDH1 could represent a potential candidate tumor suppressor gene in this region." (PMID 24165089, 2013).
tumor (continued). "The E-cadherin gene (CDH1), located on chromosome 16q22.1, is one of the most important tumor suppressor genes." (PMID 22794276, 2012). "In the tumor panel, increased promoter methylation was observed in BLU, CASP8, DCR2, CDH1, RASSF1A and RASSF2, possibly providing the second hit for BLU, RARB and RASSF1A." (PMID 22984959, 2012). "In contrast to common HCC the APC and CDH1 (E-cadherin) genes were found devoid of any DNA methylation in FLC, whereas the GSTπ1 gene showed comparable DNA methylation in tumor and surrounding tissue at a moderate level." (PMID 21060828, 2010). "The identified genes are involved in drug transport and detoxification (ABCB1, DNAJC15, GSTP1, RAB6C), DNA damage repair (BRCA1) as well as tumor cell proliferation/invasion (APC, CDH1, ESR1, HIC, PLAU, RASSF1, SULF2, TGM2)." (PMID 20544021, 2010). "RASSF1A, RARβ2, E-cadherin (CDH1), CDH13 and RIL were found to be expressed at a low level, in agreement with the hypermethylation of these genes in tumor tissues." (PMID 20642860, 2010). "In pRCC, CDH1 and RASSF1A methylation levels were inversely correlated with tumor stage (p = 0.031) and nuclear grade (p = 0.022), respectively." (PMID 17645803, 2007). "In terms of spatial localization, we also found that the neural-signal-related ligand CDH1 interacts with EGFR mainly in the tumor surrounding area, which may promote tumor invasion into normal tissues." (PMID 41147013, 2025). "No significant expression of CDH1 was observed in other tumor cell groups (Biphasic_spindled, Monophasic and Poorly_differentiated)." (PMID 41440042, 2025). "However, some studies have suggested that compensatory upregulation of CDH1 gene expression may occur in the early stages of certain cancers, potentially as an adaptive response by cancer cells to maintain a degree of cell adhesion, specific to the tumor microenvironment or cancer progression stage." (PMID 40416864, 2025). "Notably, alterations in cell adhesion molecules, such as E-cadherin (CDH1), and activation of epithelial-to-mesenchymal transition (EMT) pathways contribute to tumor invasion and metastasis." (PMID 40087784, 2025). "Additionally, NT5E can reduce intercellular adhesion by regulating cadherin-1 and vimentin, thereby inducing epithelial-mesenchymal transition (EMT) and conferring an “invasive phenotype” to tumor cells." (PMID 40612859, 2025). "In A549 NSCLC cells, KAT8 interacted with and acetylated LSD1, inhibiting LSD1 activity, which increased the methylation of histone H3 at lysine 4 in the promoters of KRT8 and cadherin 1 (CDH1/E-cadherin), upregulating their expression and promoting EMT and tumor invasion." (PMID 40508066, 2025). "The spatial coexpression of CDH1 and ERBB3 was only observed in the core region of the tumor, which may be related to the proliferation of tumor cells." (PMID 41147013, 2025). "Moreover, analysis of gene expression across pathological stages showed consistent upregulation of CDH1, CDH2, and CDH3 in advanced tumor stages, emphasizing the potential role of cadherin genes in NSCLC progression." (PMID 40860670, 2025). "However, it was only in the originating tumor tissue that SNAI2+ tumor cells displayed signs of EMT, shown by reduced E‐cadherin/CDH1 expression, which was largely restricted to cells at the tumor–stroma interface." (PMID 40600748, 2025). "Within the CDH1-dominated signaling pathway, the four tumor subpopulation cells interacted with each other, with C0 RPS4Y1+ tumor cells primarily being influenced, hinting at the evolutionary dynamics and crosstalk among tumor cells." (PMID 40230840, 2025).